FOS (Fos proto-oncogene, AP-1 transcription factor subunit)
Diseases named in the same sentence as FOS in open-access papers (continued):
Sharing a sentence is not in itself a finding about the gene and the disease.
tumor (continued). "FOS, as a subunit of the transcription factor activator protein 1(AP-1), is generally known to regulate multiple life processes and is multifunctional in different tissue types according to neuroscience and tumor-related studies." (PMID 34315853, 2021). "The tumor-promoting effects of KPNA2 via the PRDM1/c-FOS pathway were also validated in vivo." (PMID 33731128, 2021). "Interestingly, also nuclear expression of the transcription factor FOS was significantly higher in tumor tissues from digoxin-treated patients as compared to their untreated counterparts." (PMID 33534128, 2021). "In those studies, normal and/or tumor tissues that underwent warm ischemia due to delayed processing after surgical incision demonstrated increased expression of FOS, FOSB, JUN, EGR1 as well as upregulation in immune system pathways compared to tissues processes immediately." (PMID 34814833, 2021). "Moreover, we further revealed that SNHG15 executed tumor‐promoting function by sponging miR‐338‐3p and increasing the expression and activities of FOS and RAB14 for the first time." (PMID 30945457, 2019). "The FOS/JUN/ETS2 plays important roles in tumor invasion and metastasis." (PMID 25137136, 2014). "Moreover, the heterodimeric AP-1 transcription factor containing c-JUN, (which commonly dimerizes with FOS) is also necessary for muscle wasting in AH-130 tumor-bearing rats, which further implicates FOS in cancer-induced muscle wasting." (PMID 25539728, 2014). "In addition, the UPR-induced gene interactome interfaces with tumor-critical transcription factors such as FOS, HIFA, and SP1, as well as with members of the TGFβ family." (PMID 24039668, 2013). "In contrast, other studies have shown FOS to act as a tumor suppressor gene." (PMID 22236809, 2012). "They explained that the tumor-suppressor activity of FOS could be a pro-apoptotic function, which might confer increased chemoresistance on tumors with low FOS protein levels." (PMID 22236809, 2012). "Moreover, gene expression levels of ESR1/ERα (P = 0.004), BCL2 (P = 0.003), and FOS (P = 0.01) were significantly lower in grade III (n = 11) than in grade I + II (n = 22) tumor samples." (PMID 18928543, 2008). "We proposed that T5224, an inhibitor of FOS, might be an effective drug for tumor cells with LA." (PMID 40151836, 2025). "Additionally, the anticoagulant Nadroparin, targeting FOS, could be tested for its ability to influence the tumor microenvironment and reduce metastasis in HCC patients." (PMID 40074445, 2025). "Moreover, endothelial cells of the tumor frequently show nuclear FOS and/or FOSB immunostaining pattern, and a subset of cases have a FOS or FOSB gene rearrangement detectable by florescence in-situ hybridization (FISH), findings suggestive of a neoplastic process." (PMID 39998691, 2025). "In addition, FOS is a proto-oncogene that promotes tumor proliferation and metastasis." (PMID 37950195, 2023). "Importantly, hsa-miR-9-3p, hsa-miR-34c-3p and FOS were validated and were found to be correlated with tumor stages and survival, which meant they could not only regulate cellular process but could also be of valuable in clinical practice." (PMID 31277149, 2019). "However, there still existed some contradictions about the role that c-FOS might play in the tumor progression." (PMID 30228980, 2018). "We further investigated whether c-FOS is indeed involved in MSI-2-mediated tumor promotion in CC." (PMID 29073938, 2017). "However, the role of FOS in tumor development remains controversial." (PMID 26110572, 2015). "However, some more recent studies suggested that FOS may also have tumour-suppressor activity and might have a function in apoptosis." (PMID 24865347, 2014). "Thus, high BCL2 levels and/or high FOS levels may only reflect aggressiveness of the disease or may be indicative of an intact pathway that is driving tumor growth and that should be sensitive to endocrine therapy." (PMID 18928543, 2008).
tumor (continued). "JUN, FOS, STAT3, JUND and NR2F1 were up-regulated in clusters C2 and C3, leading to tumor progression and immune evasion by influencing target genes HSPA1A, CXCL9 and PDGFR." (PMID 42074110, 2026). "Beyond direct tumor growth inhibition, LD1 also regulates gene expression by upregulating CYP7A1 and downregulating c-Fos (FOS), genes closely related to FGFR4 activity." (PMID 41328353, 2026). "The therapeutic potential of SF3A3 inhibition is further validated using patient‐derived tumor‐like cell clusters (PTCs), where PEITC and the c‐FOS inhibitor T‐5224 exhibit synergistic effects in suppressing EC." (PMID 40598817, 2025). "For a deeper understanding of the oncogenic mechanisms of the C0 MAFF+ tumor cell subtype, we analyzed the TFs within this subtype and identified the top five active TFs: KLF6, ATF3, JUN, FOS, and FOSB." (PMID 40936936, 2025). "c-FOS overexpression significantly accelerated the formation of tumors after injection into SCID mice, resulting in more circulating tumor cells and lung metastases." (PMID 41233892, 2025). "Module1 (Stress response) was characterized by expression of genes such as FOS and JUN,thus representing a stress-response-related signature in tumor cells." (PMID 40406120, 2025). "Therefore, c-FOS may alter the pulmonary tumor microenvironment by mediating NET formation." (PMID 40148973, 2025). "In the invasive edge, TFs such as FOS, JUN, and FOXC2 are likely driving epithelial-to-mesenchymal transition (EMT), enabling migration, invasion, and metastasis of tumor cells." (PMID 41238550, 2025). "Our in vitro and in vivo experiments have demonstrated that FOS suppresses B-ALL leukemogenesis and serves as a bona fide tumor-suppressor downstream target of ZNF217 in B-ALL." (PMID 40093906, 2025). "The AP-1 pathway regulated by c-Jun/FOS supports CD8 + T cell cytotoxicity and the persistence of immune memory during acute infection and anti-tumor immunity." (PMID 40102789, 2025). "Top DGEs included the proto-oncogenes, FOS and FOSB, which were identified as two of the most upregulated features in tumor-infiltrating B cells." (PMID 39932553, 2025). "We investigated the tumor microenvironment (TME) of LUAD using single-cell RNA sequencing (scRNA-seq) to identify potential therapeutic vulnerabilities and FOS-driven mechanisms." (PMID 40936936, 2025). "Taking the signal CDH3 as an example, FOS is in general the dominant SSC that mediates the regulation of target genes; many tumor-related genes, including the keratins and S100 gene family, account for a substantial part of the most specific targets of CDH3." (PMID 40593827, 2025). "The peri-necrotic zone and pseudo-palisading cells around necrosis showed significantly higher mRNA levels of JUN, JUNB, FOS, and FOSL2 compared to other regions of the tumor, such as the leading-edge, infiltrating tumor, and cellular tumor." (PMID 39257581, 2024). "Our stromal score analysis showed a favourable link between the expressions of genes such as LRP1, FGF7, FOS, PI3, PAEP, and PDGFRA and tumour purity in our investigation of the effect of IRGs on OC’s TME." (PMID 39063239, 2024). "A comparison of EGR1, FOS, IER2, JUN, KLF6, MYC, and FOSL2 gene expression in 481 tumor samples revealed that individual tumors vary substantially in the expression of all analyzed genes." (PMID 39436655, 2024). "Tumor-specific CD8 + T cells exhibited higher expression levels of cytotoxicity-related genes IFNG and GZMK, immune regulators FOS and JUN, and exhaustion markers TIGIT and PDCD1." (PMID 39033098, 2024). "Tumor-specific CD4 + T cells showed higher expression levels of chemokine CXCL13, immune regulators FOS and JUN, and exhaustion markers TIGIT." (PMID 39033098, 2024). "The expressions of SHISA5, SERPINE1, and IL1A were markedly high in tumor tissues, whereas those of TP53AIP1, ETS2, and FOS were high in the normal tissues." (PMID 38435998, 2024).
tumor (continued). "Four signaling pathways—TGFβ (related to SRC), IL-1 (related to FOS), CXCL, and VEGF (related to CXCL2), were highlighted due to their significant roles in tumor occurrence, progression, and deterioration." (PMID 39770551, 2024). "Mechanistically, transcription factor activating protein 1 (AP-1) facilitates tumor metastasis and growth by occupying the promoters of JUN and FOS and activating their transcription, and H3K9me3 inhibits AP-1 activation by occupying the same binding sites." (PMID 37692513, 2023). "In 62 EBVaGC tumour tissues from the SYSUCC cohort, FOS expression was detected to be positively correlated with IGF2BP1/2 expression, suggesting an underlying positive regulatory mechanism." (PMID 38082402, 2023). "The most five active regulators were identical in tumor and normal tissues, SPI1, CEBPB, JUNB, FOS, and KLF4." (PMID 37335089, 2023). "FOS and JUN are B-cell receptor pathway modules and have been shown to be upregulated in tumor-infiltrating B cells in other solid tumors." (PMID 38110959, 2023). "HCC-CAF interactions were also enriched in the responding tumors and were associated with extracellular matrix (ECM) remodeling as there was high activation of FOS and JUN in CAFs adjacent to the tumor." (PMID 37723590, 2023). "FOS and JUN are part of the upregulated module in premalignant samples and downregulated modules in tumour samples." (PMID 38157373, 2023). "Frequently upregulated MAPK pathway genes in resistant tumours were apart from DUSP6 different FGFs, MYC, EPHA2, and FOS." (PMID 37604687, 2023). "They act on targets such as IL-6, FOS, STAT3, ERBB2, and EGF, exerting effects on delaying tumor cell resistance and inhibiting tumor cell invasion and metastasis." (PMID 37990309, 2023). "We demonstrated that the tumor suppressive is mediated by both positively and negatively acting downstream effectors, including CBX6, TRIB3, ETV4 and FOS/JUN, where the first two also affect the differentiation status of Lp30 AML." (PMID 36631623, 2023). "In the effective treatment group, the expression of inflammation, cytokines, and Toll-receptor-related genes (such as FOS, CCL4, and NR4A2) increased in the CD8+ T cells in tumor tissues after treatment." (PMID 37762493, 2023). "Conversely, c-FOS was readily detected in ER+ and GATA3+ tumor cells, but hardly detectable or weakly expressed in ER− and GATA3 weak or non-detectable tumor cells." (PMID 37353480, 2023). "Among the responders, we observed the activation of the PAX5 network in the immune regions adjacent (spatial gene expression clusters in direct contact) to tumor clusters, while FOS and JUN modules are highly active in CAFs surrounding the tumor spots." (PMID 37723590, 2023). "We noted that the DEGs between the two T-cell clusters were consistent with the DEGs identified between ERG+ and ERG− tumor cells, with FOSB, FOS, and JUN overexpressed in ERG+ tumor cells while CXCR6 and DUSP4 were overexpressed in ERG- tumor cells." (PMID 35013146, 2022). "The oncogenic transcription factors FOS and JUN, highly expressed in post-treatment tumors, were also upregulated in the stroma (tumor stroma and remission stroma) around post-treatment tumors." (PMID 36505794, 2022). "MP1 was characterized by expression of genes such as FOS and JUN, thus representing a stress-response-related signature in tumor cells." (PMID 36423636, 2022). "Dimers of FOS (c‐FOS, FOS‐B, FRA‐1/FOSL1 and FRA‐2/FOSL2) and JUN (c‐JUN, JUN‐B, and JUN‐D) build the AP1 complex, which can drive tumor progression and treatment resistance." (PMID 35604882, 2022). "AP-1 transcription factors are dimers of basic region-leucine zipper (bZIP) proteins belonging to the JUN, FOS, MAF and ATF sub-families and play important roles in cellular proliferation, survival, locomotion and tumor biology." (PMID 35267426, 2022).
tumor (continued). "Genes from FOS-JUN modules (FOS, JUN, and ERG1), MAPK/ERK, PI3K-AKT and JAK/STAT pathways, and IGF1 involved in tumor growth and resistance to AI, were upregulated in both studies." (PMID 34965950, 2022). "AP-1 is a dimeric complex that includes the JUN, FOS, ATF and MAF proteins that form diverse homodimers and heterodimers in regulating oncogenic and tumor-suppressive activities." (PMID 35022313, 2022). "Simultaneous infection of stromal and tumor cells; Upregulation of Fez1 and Pycard; Downregulation of DLL-4, Angiopoietin 2, PECAM, Tie-1, and FOS EGR2, CREB-5, IL-6, Map2K1, CCL22, TIMD4 and CCL19." (PMID 35640930, 2022). "Factors released from tumor cells feed forward to increase activation of NF-κB (NF-κB1), STAT3, and AP1 (JUN, JUNB, and FOS) in surrounding cells." (PMID 36134665, 2022). "The SPINK1 general cancer pathway and HGF signalling were activated in G3 cells in which the tumour malignancy‐related genes RASD1, PIK3R1, JUN, and FOS were significantly upregulated, indicating that G3 promotes malignant progression in GC." (PMID 35184420, 2022). "As shown in the volcano plot, SU decreased GZMB expression and upregulated genes related to inflammatory activation (FOS, JUN, NFKBIA, DUSP2, JAK1, PIM1), tumor immunity (CD47, PCBP2, EIF5A, PDIA3, EGR1), and DNA damage (H2AFX, DDIT3, GADD45B)." (PMID 34824394, 2021). "We noticed that several TF-regulating genes, including FOS and JUN, appeared to be particularly important during tumour evolution." (PMID 33441952, 2021). "Upregulated within the tumor-infiltrating CD4+ T cells were heat shock proteins (HSPA1A and HSPA1B), Jun and FOS constituents (FOS, JUN, and JUNB), MHC-II molecules (HLA-DRB), and secreted molecules (CCL5, GZMA, and GZMK)." (PMID 33504936, 2021). "Among tumor-related genes (CXCR4, FOS, DUSP10), FOS is a member of the FOS gene family and plays a regulatory role in cell proliferation, differentiation, and apoptosis." (PMID 35111153, 2021). "The top 10 downregulated genes are involved in different signalling pathways, such as the CHN2 gene in the regulation of RAC1 activity, the FOS gene in EGFR signalling and ITGA7 in integrin pathways and Akt signalling and in tumour initiation and progression." (PMID 32613561, 2020). "AP-1 transcription factor complex (composed of FOS and JUN proteins) has been identified as the main determinant in tumor progression, proliferation, migration, invasion, angiogenesis, and drug resistance." (PMID 32296574, 2020). "While FOS and MYH11 were lower in the tumor specimens compared to their normal controls, the other genes were more prevalent in the tumor specimens." (PMID 33256002, 2020). "Genetic deletion of FOS inhibited tumor growth in a BCR‐ABL fusion protein kinase‐induced CML mouse model, and therefore, inhibition of high FOS expression reduced the intrinsic resistance of CML to TKI therapy." (PMID 31373443, 2019). "However, mutations of FOS have not been found in human bone-forming tumours." (PMID 29858576, 2018). "Combining whole-genome DNA and RNA sequences, we find rearrangement of FOS in five tumours and of FOSB in one tumour." (PMID 29858576, 2018). "The boxplots showed that the expression level of EGR1, FOS, and FOSB was significantly lower in primary tumor than that in the normal liver for LIHC patients from TCGA (p<0.001)." (PMID 30228980, 2018). "Herein, we identify RASAL2 as a novel tumor suppressor in RCC, and it can inhibit RCC angiogenesis via p-GSK3β/c-FOS/VEGFA pathway." (PMID 30158581, 2018). "Taken together, our results indicate that anti‐EGFR therapies will be successful in patients with FOS‐positive OS, where EGFR seems to be a tumor driver." (PMID 30361264, 2018).
tumor (continued). "Given that FOS and FGF18 are involved in tumor growth, and invasion as well as PFDA stimulates cell growth and, the microarray data seemed to imply us that PFDA were involved in the processes of tumorigenesis." (PMID 28881615, 2017). "This pathway includes well-known cancer-related genes such as FOS, TGFB3 and TGFB1 that increased connectivity in the tumor network." (PMID 25253512, 2014). "We also observed that transfection EZH2, MCL-1 and FOS siRNA significantly inhibited the ability of SPAC-1-L and HEC-50 cells to invade and to form spheres, mimicking the tumor suppressive effects upon miR-101 overexpression." (PMID 25153722, 2014). "In the case of a possible tumor suppressor, BNIP3L, the combination of TFs FOS and PU1 binding to the gene’s promoter (as observed in GM12878 cells) predicted the gene’s expression accurately only in B-cells." (PMID 22721266, 2012). "Tumor stromal pathways are also in evidence with the common genes including; TLR4, TLR7, HLA-DRA, HLA-DQA1, CXCR4, FOS and TGFB2 (immune surveillance and chemokine pathways) and NF2, ITGA7, PGF, ITGA4, PDGFD and PARVA (focal adhesion)." (PMID 23226201, 2012). "We then investigated the expression of ESR1/ERα and that of the five following top-ranked genes (MET, FOS, SNCG, IGFBP4, and BCL2) by RTQ-PCR on the initial set of 18 tumor samples (eight control and 10 TF)." (PMID 18928543, 2008). "Expression of the other two genes, FOS and TGFBR2, is reduced in tumor tissues, which is in agreement with the literature." (PMID 19087325, 2008). "Oncogene activation by genomic amplification, which usually occurs during tumour progression, is seen in the members of different oncogene families including MYC, CCND, EGFR, and FOS." (PMID 19506729, 2008). "Median survival was shorter for patients with ERBB-1-, VEGF-, cyclin A-, FOS-, or JUN-positive tumours." (PMID 9484827, 1998). "Furthermore, transcription factors FOS and JUNB showed robust correlations with CXCL2 and HBEGF, suggesting multiple molecular mechanisms regulating tumor angiogenesis in Transitional Mono to M0 cells." (PMID 41514936, 2026). "In CRC, however, SLC46A1 downregulation induces intracellular folate deficiency, triggering locus-specific DNA hypomethylation at the FOS promoter, which activates oncogenic transcription of key downstream effectors (CCND1, BCL2, PLAU), driving tumor progression." (PMID 41620398, 2026). "Together, this work demonstrates that FOS and JUN may function in coordinating the redox-steroidogenesis axis, linking molecular changes in the adjacent cortex to tumor function and microenvironmental remodeling." (PMID 41412035, 2025). "Oliver H. Krämer and Günter Schneider reviewed the potential of combining c-FOS and HDAC inhibitors (HDACi) in DLBCL, noting that this combined strategy might enhance anti-tumor efficacy through the modulation of epigenetic modifications." (PMID 40270607, 2025). "Additionally, the downregulation of c-FOS effectively inhibits the NET formation and hence leads to controlled tumor growth and lung metastasis." (PMID 40148973, 2025). "To sum up, we speculate that c-FOS may promote lung metastasis in TNBC by directly regulating the NET formation and therefore can realize the restructuring of the tumor immune microenvironment." (PMID 40148973, 2025). "The KLF6, MYC, and FOSL2 genes did not seem to follow the EGR1/FOS expression pattern in the analyzed tumor samples." (PMID 39436655, 2024).